EGFR (epidermal growth factor receptor)
Diseases named in the same sentence as EGFR in open-access papers (continued):
Sharing a sentence is not in itself a finding about the gene and the disease.
breast carcinoma (continued). "With that in mind, we explored a publicly available dataset on breast cancer and identified that ER-negative, RANK-c positive samples presented with reduced phosphorylation of EGFR protein, corroborating our previous findings on RANK-c mode of action on EGFR." (PMID 34828291, 2021). "Drawing conclusions from the reviewed data in humans and companion animals, combinations should eventually be considered for the treatment of OSA (including EGFR or PDGFR targeting), HNSCC (with c-Kit inhibition), and mammary carcinoma (using multi-TKIs)." (PMID 33664868, 2021). "Most of them are able to target EGFR, PDGFR, vascular endothelial growth factor receptors (VEGFR) known targets of GBM or even HER2, a target in breast cancers." (PMID 33918704, 2021). "Combined treatment with leptin and EGFR inhibitor, AG1478, inhibited leptin-induced Med1 phosphorylation in comparison to breast cancer cells treated with leptin alone." (PMID 34389732, 2021). "In HER2 amplified breast cancers and colorectal cancers, an anti-HER2 monoclonal antibody Trastuzumab can be combined with another monoclonal antibody Pertuzumab or with an EGFR/HER2 dual kinase inhibitor Lapatinib." (PMID 34461089, 2021). "Overall, these pre-clinical findings originally suggested that EGFR- and HER2-targeted therapies would disrupt both genomic and non-genomic cross-talk with the ER, and consequently re-sensitize breast cancer cells to tamoxifen and other endocrine therapies." (PMID 33800852, 2021). "In mice, this led to an activation of epidermal growth factor receptor (EGFR) and subsequent increases in growth factor expression related to mammary carcinoma." (PMID 34858639, 2021). "Members of the human epidermal growth factor receptor (HER/ERBB) family, including EGFR (HER1), HER2, HER3, and HER4, display tyrosine kinase (TK) activity and play key roles in breast cancer." (PMID 34290605, 2021). "To further validate the result, we analyzed tissue specimens from HMUCC, and we found that EGFR, JAK2, and STAT3 were upregulated in breast-cancer tissues relative to the expression in normal tissues." (PMID 33446634, 2021). "We measured protein levels of two receptor tyrosine kinases, Epidermal Growth Factor Receptor (EGFR) and Insulin-like Growth Factor 1 Receptor (IGF-1R), both critical in the processes leading to metastasis in breast cancer." (PMID 34238275, 2021). "EREG can induce the Warburg effect through EGFR signaling activation, which increases the expression of glycolytic genes, including GLUT3, HK2, and PDK1, in breast cancer cells resistant to tamoxifen." (PMID 34884633, 2021). "SKBR3 therapy sensitive EGFR and HER2 positive human breast cancer cells were created following exposure of the cells to gefitinib (0.1 or 0.5 μM) or lapatinib (0.1 μM)." (PMID 34074257, 2021). "The repurposed compounds with the highest affinity for EGFR and HER2 showed growth inhibitory activity in two different breast cancer cell lines, MCF-7 and MDA-MB-231, at micromolar concentrations." (PMID 34451888, 2021). "In MDA-MB-231 breast cancer cells, CD44, neuropilin 1, plexin A1 and B2, EGFR, as well as various CAM proteins, namely nectin-like protein 5, ALCAM, L1CAM and MUC18, were identified as cathepsin substrates." (PMID 33809973, 2021). "Various αTAA–αCD3 and αTAA–αCD28 BiMAb in a tetravalent IgG1-Fc based format have been analyzed, targeting multiple breast cancer antigens including HER2, EGFR, CEA, and EpCAM." (PMID 34484225, 2021). "In the clinic, the dual EGFR/ERBB2 inhibitors lapatinib and neratinib are used as therapies for ERBB2/HER2-positive breast cancer." (PMID 34737261, 2021). "Grape seed extract inhibits the expression of the epidermal growth factor receptor (EGFR) in head and neck cutaneous squamous cell carcinoma, and of MEPK/ERK1-2 and MAPK/p38 in breast cancer, counteracting tumor invasiveness and progression." (PMID 34209556, 2021).
breast carcinoma (continued). "Neratinib (tyrosine kinase inhibitor) inhibited the action of proteins by binding with adenosine triphosphate (ATP), leading to the inhibition of phosphorylation on EGFR, HER2, HER3, HER4, AKT and ERK inSKBR3 and BT474 cells (HER2+ breast cancer cells)." (PMID 34361688, 2021). "One cell membrane protein target that has been identified is the epidermal growth factor receptor (EGFR), which is overexpressed in several tumors of epithelial origin including breast cancers of ductal or lobular origin." (PMID 34831131, 2021). "All patient-specific subnetworks contained relevant drug targets that have been largely studied in breast cancer (e.g., ERBB2, ESR1, EGFR, AKT1)." (PMID 33706810, 2021). "The treatment of ER-α-positive breast cancer cells with tamoxifen can lead to resistance, and IGF-IR and/or EGFR are critical for breast cancer resistance to endocrine therapy." (PMID 35011656, 2021). "As a resident, José led many clinical trials and showed the potential of targeting HER2 in breast cancer patients with HER2 overexpression and of targeting EGFR using cetuximab in EGFR-overexpressing tumors." (PMID 33962670, 2021). "Lapatinib is an FDA-approved EGFR and HER2 tyrosine kinase inhibitor for the treatment of HER2-positive breast cancer patients." (PMID 34290605, 2021). "MDA-MB-468-NEO (EGFR positive) and MDA-MB-468-HER2 (EGFR and HER2 positive) human breast cancer cells were used in this study." (PMID 33832505, 2021). "Meanwhile, EGFR (p = 0.008), RAC1 (p = 0.03) and VEGF-B (p = 0.0004) genes expression in mammary carcinoma tissue were higher in the high proliferation index group (≥14%) than in low proliferation index group (<14%)." (PMID 34679042, 2021). "Nuclear EGFR cooperates with STAT3 and promotes inducible nitric oxide synthase (iNOS) expression, which has been reported to promote breast cancer metastasis." (PMID 34298665, 2021). "The use of lapatinib, a dual EGFR/HER2 therapeutic, has improved breast cancer patient survival when used in combination with HER2-targeted therapeutics such as trastuzumab." (PMID 34074257, 2021). "In breast cancer cells, SHP-2 was found to enhance RTK activity such as EGFR and FGFR1 as well as downstream MAPK/ERK and PI3K-AKT signaling." (PMID 34884670, 2021). "The aberrant EGFR activation controls cell migration, at least in part, through RAC1, which is overexpressed in human breast cancer cells." (PMID 33633298, 2021). "It is reported that ANO1 interacts with EGFR and affects EGFR-targeted therapy in HNSCC and breast cancer." (PMID 33901011, 2021). "Neratinib displayed the greatest anti-proliferative activity against HER2-mutant and EGFR-mutant models compared to the other HER2-targeted TKIs and was the most potent of the three TKIs in breast cancer models." (PMID 33473169, 2021). "To examine the roles of the CUL3/KCTD10 complex in the activation of EGFR and HER2, we first examined the phosphorylation of those receptors in HER2-positive breast cancer cells." (PMID 34187934, 2021). "They include associations of methylation of regions of the ABL2 oncogene in breast cancer and in COAD/READ, and of the epidermal growth factor receptor EGFR gene in CLLE." (PMID 33676569, 2021). "The conclusion of ERBB2 inhibition of autophagy was drawn mainly based on the observation that lapatinib, an inhibitor for both EGFR and ERBB2 tyrosine kinases, increased autophagy in ERBB2-expressing breast cancer cells." (PMID 33801244, 2021). "Lapatinib treatment of HER2-positive breast cancer cell lines was shown to inhibit HER2 and EGFR activity as well as downstream phosphorylation of Akt and ERK." (PMID 34208071, 2021). "ErbB1/HER1, known as EGFR, was discovered as an oncogenic target in NSCLC, glioblastoma, and basal-like breast cancers." (PMID 35004854, 2021).
breast carcinoma (continued). "In this study, we found that depletion of CUL3 or KCTD10 reduced the phosphorylation of EGFR and HER2, as well as cell proliferation of HER2-positive breast cancer cells." (PMID 34187934, 2021). "ERβ suppression inhibits EMT and reduces the expression levels of MMP1, 2, 7, 9 and 14 following reduced ERK1/2 activation stimulated by EGFR/IGF-IR and JAK2/STAT5-mediated migration in breast cancer cells." (PMID 33809973, 2021). "Exosomes expressing cetuximab scfv recognize and kill EGFR-positive cells while exosomes expressing trastuzumab scfv recognize and kill HER-2 positive cells in breast cancer." (PMID 33808645, 2021). "The EGFR/HER2 dual inhibitors, lapatinib and neratinib, which have similar half-maximal inhibitory concentration (IC50) values for EGFR and HER2, have been approved for patients with HER2-positive breast cancer." (PMID 34207383, 2021). "Epidermal growth factor receptor (EGFR) and human EGFR 2 (HER2) phosphorylation drives HER2-positive breast cancer cell proliferation." (PMID 34187934, 2021). "While in breast cancer (BC), GDI2 was found to contribute to EGFR endocytosis and thus enhance EGFR signaling and metastasis formation." (PMID 34894398, 2021). "Specific targeting of chimeric MrNV to EGFR was proven by both EGFR silencing with siRNA vector and a competition with excess GE-11 peptide as well as the use of EGFR-negative colorectal cells (SW620) and breast cancer cells (MCF7)." (PMID 34400669, 2021). "We subsequently divided all 160 breast cancer cases into 4 groups: a high SHP-1 and high EGFR expression group, a high SHP-1 and low EGFR expression group, a low SHP-1 and high EGFR expression group, and a low SHP-1 and low EGFR expression group." (PMID 34591414, 2021). "We verified the effects of ruthenium-fluvastatin complex treatment on various proteins like PI3K, Akt, mTOR, EGFR, VEGF, and cleaved caspase-3 in MCF-7 and MDA-MB-231 human breast cancer cells." (PMID 34221232, 2021). "HER2, a member of the Erythroblastosis Protein B/Human Epidermal Growth Factor Receptor (ErbB/HER) family of receptor tyrosine kinase, is overexpressed in 20~30% of human breast cancers." (PMID 33557368, 2021). "Compared with EGF, EREG resulted in a weaker EGFR dimer with a shorter life span, which triggered aberrant EGFR signaling and sustained ERK pathways, leading to breast cancer cell differentiation." (PMID 34884633, 2021). "Lapatinib, a dual EGFR and HER2 inhibitor, are clinically effective against HER2-amplified breast cancer by blocking HER2 phosphorylation, resulting in inhibition of downstream PI3K/AKT and MAPK pathways." (PMID 34399705, 2021). "In non-small-cell lung cancer (NSCLC), breast cancer, and colorectal cancer (CRC), the EGFR was also found to be expressed in nuclei." (PMID 34298665, 2021). "Due to these advantages over first-generation EGFR inhibitors, afatinib also was investigated against cancer cells exhibiting abnormalities of the ErbB network such as NSCLC and breast cancer." (PMID 34771085, 2021). "Lapatinib is the first dual inhibitor of EGFR and ERBB2/HER2 for treating ERBB2-positive breast cancer, whereas brigatinib is a mixed inhibitor of ALK and EGFR used for the treatment of metastatic NSCLC." (PMID 34607583, 2021). "Neratinib, a next-generation irreversible small molecule inhibitor of receptor tyrosine kinases (HER1/EGFR, HER2, and HER4), has been recently approved for the treatment of HER2+ breast cancer." (PMID 34556812, 2021). "We also analyzed the EGFR expression and found its levels were enriched in CTC clusters compared to single CTCs isolated from the blood of breast cancer patients." (PMID 33995681, 2021).
breast carcinoma (continued). "Our present results suggest that CNKSR1 serves as an oncoprotein by inactivating PTPRH, a tumor-suppressive EGFR phosphatase, in HER2-positive breast cancer cells." (PMID 34187934, 2021). "Neratinib is an irreversible inhibitor of the EGFR, HER2/4 receptor tyrosine kinase, which was approved on 17 July 2017 for use in the treatment of HER2-positive breast cancer." (PMID 34771085, 2021). "Thus, the drug may have acted on the few HER2 molecules present, and in the case of the cell line UNESP-MM1, the action could be related to binding to EGFR, this ability of lapatinib to inhibit EGFR phosphorylation has already been described in feline mammary cancer cells." (PMID 34204236, 2021). "In this study, we also describe the clinical validation of the FoundationOne Liquid CDx assay, including large-scale comparisons with orthogonal clinical plasma- and tissue-genotyping methods, for both EGFR in NSCLC and PIK3CA in breast cancer." (PMID 32976510, 2020). "This was seen for EGFR+ cancer cells opsonized with cetuximab, as well as for trastuzumab-coated HER2/neu+ human breast cancer SKBR3 cells." (PMID 32983165, 2020). "Our group first explored the concept of combining anti-EGFR CAR NK cells and oncolytic virus therapy in a metastatic breast cancer animal model." (PMID 33287875, 2020). "Lapatinib (Tykerb /Tyverb) is a dual tyrosine kinase inhibitor which interrupts the HER2/neu receptor (human EGFR type 2) and epidermal growth factor receptor (EGFR) signaling and it is used to treat HER2-positive breast cancers." (PMID 32365111, 2020). "SKBR3 and BT-474 cells have been widely used by investigators interested in HER2 amplification and overexpression in breast cancer, and MDA-MB-468 cells have been often used to study EGFR signaling in breast cancer." (PMID 32715085, 2020). "The constitutive activation of tyrosine kinases of the epidermal growth factor receptor (EGFR) family, and of the downstream signaling pathway, was suggested as a key step in supporting the aggressive phenotype of breast cancer cells." (PMID 32498343, 2020). "Activation and overexpression of epidermal growth factor receptor (EGFR, also known as ErbB) family members, including EGFR (ErbB1 or HER1), HER3 (ErbB3), HER4 (ErbB4), and HER2 (ErbB2), govern multiple important cellular processes in breast cancer." (PMID 32223744, 2020). "Here, we show that honeybee venom and melittin suppress the ligand-induced phosphorylation of EGFR and HER2, dynamically modulating downstream signaling pathways in breast cancer cells." (PMID 32923684, 2020). "Compound 38a markedly decreased p-EGFR and p-PI3K expression, which revealed that compound 38a targeted breast cancer cells via interference with the EGFR-PI3K signaling pathway." (PMID 32326131, 2020). "Pearson correlation analysis was performed to assess the relationships between EGFR and BIRC5 expression and clinical characteristics of breast cancer patients using the 855-patient dataset." (PMID 32001757, 2020). "cugWT1 is highly expressed in breast cancer cells, which can mediate tumor cell transformation and up-regulate c-MYC, BCL2, and EGFR expression; silencing it leads to decreased anchorage-independent growth and proliferation of breast cancer cells." (PMID 32210734, 2020). "We have previously shown the ability of the natural compound EGCG to inhibit FASN activity in wild type EGFR NSCLC cells and different breast cancer subtypes." (PMID 32438613, 2020). "We subsequently investigated if both honeybee venom and melittin disrupt RTK-associated signaling pathways by blocking the ligand-dependent activation of EGFR and HER2 in breast carcinoma cells." (PMID 32923684, 2020). "Apart from EGFR, transcriptomic and protein analyses on HER2-amplified breast cancer cell lines showed enhanced FASN expression modulated through the PI3K-dependent pathway." (PMID 32872164, 2020).
breast carcinoma (continued). "Whereas the potential role of EGFR-targeted treatments in breast cancer is still undetermined, treatments targeting HER2 have radically improved outcomes for breast cancer patients with tumors overexpressing HER27,8." (PMID 33024132, 2020). "According to data analysed by Oncomine, mucinous breast carcinoma was the only breast tumour that had high expression of PTGS2, EGFR, and ABCB1, suggesting that expression of these genes vary based on breast cancer type." (PMID 32577155, 2020). "Here, a method is presented for the simultaneous detection of individual EGFR and HER2 receptors in the plasma membrane of breast cancer cells via specific labeling with quantum dot nanoparticles (QDs)." (PMID 33260837, 2020). "In summary, we have identified specific oncogenic functions of the TGFβ-SMAD, EGFR, and p63 pathways in EMT and invasion of HER2+ and/or EGFR+ breast cancer cells." (PMID 32350443, 2020). "Case presentation: We report a case of breast cancer coexisting with HER-2 amplification and EGFR exon 19 deletion (E19 del)." (PMID 32547945, 2020). "We found that through the phosphorylation of EGFR at T654, HUNK significantly increased metastatic phenotypes in breast cancer cells and mammary tumor metastasis in vivo." (PMID 31597954, 2020). "In SKBR3 cells, an immortalized breast cancer cell line serving as a common model for HER2 driven breast cancer, HER2 expression is 20-fold higher in average compared to EGFR." (PMID 33260837, 2020). "Since CDR1as has been previously shown to modulate EGFR and KLF4 in breast cancer development, and these genes play importat roles also in the skin, it will be interesting to assess its potential tumor suppressive effect in the context of cSCC." (PMID 32108138, 2020). "The observed reduction in STAT1 expression suggests a feedback regulatory mechanism of pSTAT1 on its own promoter, already documented, as well as an EGFR/HER2-dependent regulation as previously shown in glioblastoma and breast cancer cell lines." (PMID 32642677, 2020). "EV proteins isolated from the plasma of 30 pre-operative breast cancer patients and 20 healthy patients were introduced into the immunosensor followed by HRP-conjugated anti-EGFR antibody." (PMID 33143170, 2020). "In breast cancer, GPRC5A has been reported to be downregulated and was identified to act as a tumor suppressor by RhoA/C and EGFR related signaling pathway." (PMID 33680947, 2020). "In human breast cancer, CD73 had a regulatory effect on EGFR expression and phosphorylation, which correlated with tumour growth." (PMID 33187081, 2020). "In breast cancer cell lines, MDGI plays an important role in EGFR subcellular relocalization into an intracellular pool where the receptor is active but in a compartment that renders anti-EGFR antibody therapy inefficient." (PMID 32377505, 2020). "Phosphatase PTP1B dephosphorylates tyrosine kinases essential for the induction of breast cancer, such as HER1/EGFR, Src, JAK, and STAT, and initiates tumor formation." (PMID 33266280, 2020). "Most importantly, this is the first study to highlight EGFR T654 phosphorylation as a mechanism for breast cancer metastasis, and the first to show that pharmacological inhibition of HUNK impairs breast cancer metastasis." (PMID 31597954, 2020). "Combining berberine with the dual EGFR and HER receptor inhibitor lapatinib was shown to decrease the lapatinib-resistance of breast cancer cells." (PMID 32365809, 2020). "CCL20 expression is also upregulated in tumour cells isolated from melanoma, breast cancer, colon carcinoma and head and neck squamous cell carcinoma (HNSCC) patients, in conjunction with activation of the EGFR/Ras-signalling pathway." (PMID 32601464, 2020).